INSR (insulin receptor)
Diseases named in the same sentence as INSR in open-access papers (continued):
Sharing a sentence is not in itself a finding about the gene and the disease.
gastric cancer (11 papers, 2013 to 2024). A primary or metastatic malignant neoplasm involving the stomach. "Using the metabolic pathway genes for glucose metabolism, we found that INSR expression was consistently elevated from premalignant lesions to gastric cancer, while high expression of INSR predicted lower survival rates." (PMID 35755820, 2022). "That patients whose tumour cells have higher INSR expression, and a priori higher insulin receptor levels, have worse survival implies that insulin promotes gastric cancer." (PMID 34554347, 2022). "We found the insulin receptor (IR) to be overexpressed not only in cancer cells, but also in the cancer vasculature of colorectal and gastric cancer samples." (PMID 34638472, 2021). "Metabolic reprogramming in gastric cancer (GC) involves not only an alteration of glucose metabolism, but also of insulin receptor (IR) expression." (PMID 30989432, 2019). "The insulin receptor (INSR) regulates the insulin signaling pathway and activates the oncogenic PI3K/Akt/mTOR pathway, and its high expression is inversely associated with patient survival in ccRCC and gastric cancer." (PMID 38673800, 2024). "Notably, insulin receptor levels are visualised easily in three of the four gastric cancer cell lines and in the metastatic cells that represent the majority of gastric cancers that are triple-negative for ERBB2, FGFR2 or MET overexpression." (PMID 34554347, 2022). "In gastric cancer, the high expression of INSR correlates with HER2 status and may have putative therapeutic implications." (PMID 35654816, 2022). "Surprisingly, the three KIs share the same target, ALK and INSR, but only the ALK gene was found to have a high expression level in the gastric cancer cell line." (PMID 36145589, 2022). "Interestingly, the three molecules share the same targets, ALK and INSR, in which only the ALK gene is overexpressed in the gastric cancer cell line." (PMID 36145589, 2022).
cognitive decline (10 papers, 2015 to 2024). "A large number of studies in the last two decades suggest that central insulin resistance and cognitive decline in AD are associated with changes in the neuronal insulin/IR signal transduction cascade, insulin grow factor 1 (IGF-1) resistance and insulin receptor substrate 1 (IRS-1) dysregulation." (PMID 37445790, 2023). "Collectively, the data suggest that neddylation and degradation of the insulin-receptor substrate is a nodal point that links high amyloid load, neuroinflammation, and synaptic insulin resistance to cognitive decline and impaired synaptic plasticity in high-risk aging." (PMID 34986876, 2022). "Dapa improved hippocampal synaptic plasticity and prevented cognitive decline by restoring the phosphorylation levels of the insulin receptor, Akt/PKB, and NFκB p65 in HFD-induced obese rats." (PMID 38255143, 2023). "Impaired insulin (InsR) and insulin growth factor receptor (IGF-1R) signaling via pAkt/Akt has been linked to cognitive decline in normal aging, as well as AD." (PMID 30631278, 2018). "Additionally, more in-depth investigations have shown reduced insulin receptor density in the brains of individuals with cognitive decline, along with impairment in downstream insulin signaling pathways." (PMID 37950317, 2023). "The Morris water maze test was then performed to evaluate decreases in cognitive function, and western blot was used to verify whether abnormal insulin receptor signaling was induced by ERS in HFD rats exhibiting cognitive decline." (PMID 25978724, 2015). "In addition, insulin receptor signaling was impaired more significantly in the hippocampus, which was indicative of cognitive decline." (PMID 25978724, 2015). "However, when this genetic model was crossed with a mouse model of AD, loss of the astrocytic INSR resulted in further impaired cognition and enhanced amyloid plaque deposition, indicating a protective role of the astrocytic INSR against AD pathology and cognitive decline." (PMID 37611907, 2024). "Furthermore, insulin receptor resistance leading to dysfunction, and cerebral small vessel disease are also important when discussing the complex pathways contributing to hypoglycemic cognitive decline." (PMID 37372995, 2023).
colon carcinoma (10 papers, 2012 to 2025). "High expression of INSR, a vital gene of the glucose metabolic pathway, has a lower survival rate in colon cancer." (PMID 35755820, 2022). "This led to the hypothesis that elevated insulin receptor protein expression in colonic tumors might be a possible mechanism for tumorigenesis." (PMID 30486335, 2018).
Ewing sarcoma (10 papers, 2011 to 2025). A small round cell tumor that lacks morphologic, immunohistochemical, and electron microscopic evidence of neuroectodermal differentiation. "Compensatory activation of the insulin receptor (IR) and its mitogenic ligand IGF2 is triggered in some Ewing sarcoma cells in response to IGF2BP3 mediated IGF1R loss." (PMID 40442778, 2025). "Biochemical and histological/immunohistochemical ex vivo analyses confirmed a reduced activation of ERBB4, EGFR, INSR, IGF1R, associated with apoptosis induction and angiogenesis inhibition in a drug-treated Ewing's sarcoma family tumor xenograft." (PMID 27374103, 2016). "The closely related RTK insulin receptor (INSR), whose overexpression is a proposed mechanism of resistance to ganitumab in Ewing's Sarcoma, was also assessed." (PMID 25344862, 2014). "Ewing sarcoma cells consistently express IGF-1R and insulin receptor (IR)." (PMID 22577336, 2012).
glioblastoma (10 papers, 2015 to 2026). The most malignant astrocytic tumor (WHO grade IV). "Insulin receptor recycling frees insulin receptors to engage in downstream signaling regulating cell proliferation, which worsens glioblastoma prognosis and mediates treatment resistance." (PMID 36497269, 2022). "ZKK-3 also inhibits insulin-like growth factor-1 receptor (IGF-1R) and insulin receptor (IR) kinases overexpressed by glioblastoma." (PMID 35214064, 2022). "In brain tumors, IGF1R is frequently activated in medulloblastoma, and INSR and IGF1R are frequently activated in glioblastoma." (PMID 31480400, 2019). "Consequently, amplification of INSR in glioblastoma may enhance proliferation." (PMID 25679508, 2015).
schizophrenia (10 papers, 2010 to 2025). A major psychotic disorder characterized by abnormalities in the perception or expression of reality. "In another study, INSR SNPs rs747721248 and rs2229431 were significantly associated with schizophrenia." (PMID 40430072, 2025). "Two homozygous rare deleterious variants in INSR (c.2232-7T>G) and NFXL1 (c.1322G>A; p.Cys441Tyr) were identified, which segregated with severe treatment-resistant psychosis/schizophrenia in two families." (PMID 40430072, 2025). "In fact, it has been shown that the decrease in the insulin receptor in the brain, as seen in schizophrenia, leads to HK mitochondrial detachment." (PMID 36674678, 2023). "This hypothesis is in line with observations of a dysfunctional cerebral insulin receptor signaling in dorsolateral prefrontal cortex tissue from patients with schizophrenia." (PMID 20631894, 2010). "For instance, schizophrenia is a chronic neurodevelopmental disorder that affects approximately 1.1% of the US population, and decreased insulin receptor protein and activity and altered downstream signaling have been reported in post-mortem schizophrenia patients." (PMID 20230616, 2010).
type A insulin resistance syndrome (10 papers, 2016 to 2026). "A diagnosis of type A insulin resistance syndrome was considered, and INSR gene mutation analysis was performed." (PMID 38289143, 2024). "Insulin resistance syndrome type A can be caused by heterozygous, homozygous, or compound heterozygous variant mutations in the INSR gene (MIM#147670)." (PMID 38162681, 2023). "Type A insulin resistance syndrome (IRS) is caused by mutations in the insulin receptor (INSR) gene." (PMID 37042492, 2023). "Type A Insulin resistance syndrome (TAIRS) is an autosomal dominant or recessive genetic disorder caused by insulin dysfunction resulting from insulin receptor (INSR) gene mutation." (PMID 35634501, 2022). "Through the findings of clinical and laboratory examination, type A insulin resistance syndrome was considered and INSR mutation analyses were planned." (PMID 32018348, 2020). "We report a novel, homozygous mutation, p.Leu260Arg in exon 3, of the INSR gene in a female adolescent patient with type A insulin resistance syndrome together with clinical details of her medical follow-up." (PMID 32018348, 2020). "In this article, we report an adolescent with type A insulin resistance syndrome due to a novel homozygous mutation in the INSR gene and also report details of three years of medical follow-up." (PMID 32018348, 2020). "In conclusion, we report a novel, homozygous mutation, p.Leu260Arg, in exon 3 of the INSR gene in a patient with type A insulin resistance syndrome." (PMID 32018348, 2020). "Type A insulin resistance syndrome (TAIRS) is a rare genetic disorder resulting from mutations in the insulin receptor (INSR) gene and may be inherited in either an autosomal dominant or autosomal recessive manner." (PMID 42272804, 2026). "In segregation analysis, the same variant was detected in the patient's mother, who had a milder clinical phenotype.We reported a novel, heterozygous, p.Arg1163_Ala1168del mutation in exon 19 of the INSR gene in a patient with type A insulin resistance syndrome, expanding the mutation database." (PMID 38289143, 2024).
autoimmune disease (9 papers, 2016 to 2026). A disorder resulting from loss of function or tissue destruction of an organ or multiple organs, arising from humoral or cellular immune responses of the individual to their own tissue constituents. "Type B insulin resistance syndrome (TBIRS) is a rare autoimmune disorder associated with the circulation of anti-INSR antibodies." (PMID 38392069, 2024). "TBIRS is defined as “a distinct autoimmune disorder resulting in altered insulin signaling, which is directly attributable to circulating anti-INSR antibodies (AIRAs)”." (PMID 38392069, 2024). "As another important etiology of EHH, TBIRS is a very rare autoimmune disorder characterized by circulating polyclonal autoantibodies against the insulin receptor, disrupting glucose homeostasis." (PMID 36459334, 2023). "There are no reports of increased incidence of autoimmune disease in those with insulin receptor mutations and type A insulin resistance." (PMID 38461278, 2024). "Last but not least, considering the lack of specific INSR inhibitor and the colitis-exacerbating effect of co-inhibitors, the development of insulin-specific inhibitors is urgently needed to study the INSR-targeted therapy for patients with IBD or other autoimmunity disease." (PMID 38243324, 2024). "However, the mechanisms for the development of anti-insulin-receptor antibodies in this autoimmune disorder remain unknown." (PMID 27142369, 2016). "TNF-α, a key cytokine, plays a significant role in autoimmune diseases, with TNF-α inhibitors revolutionizing their treatment; they achieve this by impairing insulin signalling by increasing the serine phosphorylation of insulin receptor substrates, leading to decreased insulin sensitivity." (PMID 40407536, 2025). "Finally, 25 patients (8.5% of the cohort) presented with other rare severe insulin-resistance syndromes, not elsewhere specified, including patients with genetic or autoimmune diseases affecting insulin receptor, or with premature ageing syndromes." (PMID 38678257, 2024).
hyperandrogenism (9 papers, 2017 to 2025). Excessive secretion of androgens from the adrenal glands or gonads. "Heterozygous INSR mutations, manifesting as type A IR, are under-recognised in clinical practice due to overlapping features of hyperandrogenism in women." (PMID 38461278, 2024). "Moreover, GnRH analogs may be options forwomen with severe hyperandrogenism caused by insulin receptor mutations, who mightotherwise require oophorectomy." (PMID 27911591, 2017). "We now describe 6 patients (including P13) with SIR (2 with type B IR, 2 with pathogenic INSR variants, 1 with a pathogenic variant in TBC1D4, and 1 with acquired partial lipodystrophy associated with juvenile dermatomyositis) who received GnRH analogue therapy for management of hyperandrogenism." (PMID 33901270, 2021).
liver fibrosis (9 papers, 2010 to 2025). "Our previous study presented a hepatic kinome atlas in cirrhotic human liver and hepatic fibrosis rodent models using PamGene technology and found both had INSR hyperactivity." (PMID 40022609, 2025). "We further used Western blotting to test the expression of liver fibrosis-related biomarkers, and found that the inhibition of INSR expression decreased E-cadherin expression, but increased N-cadherin and a-SMA expression." (PMID 36204709, 2022). "In considering these differences, body weight may be a significant contributor to the insulin receptor responsiveness in patients with liver fibrosis or cirrhosis." (PMID 40985048, 2025). "Meanwhile, LCA may exert an acceleration effect on H-L + HFD-induced liver fibrosis by targeting liver INSR signaling." (PMID 36204709, 2022). "However, the possible effect would be much less strong than that exerted by other genetic variants, such as those influencing insulin receptor signaling and the PNPLA3 rs738409 SNP, which were significantly associated with liver fibrosis in the same series." (PMID 20825652, 2010). "Our findings can guide future studies on INSR and HSC function and how they affect MASH and end‐stage liver fibrosis in cirrhotic patients, who usually experience high bilirubin levels." (PMID 40022609, 2025). "The insulin receptor (INSR) has been shown to be hyperactive in hepatic stellate cells (HSCs) in humans and rodents with liver fibrosis." (PMID 40022609, 2025).
non-alcoholic fatty liver disease (9 papers, 2019 to 2025). "Six of the key metagenes—INSR, MAP3K5, NDUFB8, NDUFS1, SDHB, and UQCRC2—are involved in nonalcoholic fatty liver disease (hsa04932), which is caused by a defect in insulin suppression of free fatty acid (FAA) disposal due to the induction of insulin resistance." (PMID 36979367, 2023). "In adipocytes, c-Jun regulates HMGB1 secretion which bears strong correlation with non-alcoholic fatty liver disease (NAFLD) onset, primarily driven by the downstream effectors of insulin receptor." (PMID 39682695, 2024). "NEFA may then accumulate in the liver and initiate non-alcoholic fatty liver disease (NAFLD), and increase concentrations of lipid intermediates that ultimately block the insulin receptor pathway in hepatocytes." (PMID 38786765, 2024).
steatosis (9 papers, 2011 to 2025). Increased lipid within the cytoplasm of cells. "In total, we identified 27 genes, of which 3 are monogenic causes of steatosis (APOB, G6PC1, PPARG), 4 were previously associated with MASLD (APOB, APOC3, INSR, PPARG), and 23 had supporting clinical, experimental, and/or genetic evidence." (PMID 40065360, 2025). "In another study, mice double-heterozygous for the insulin receptor and Timp3 that were placed on a high fat diet developed macrovesicular steatosis and showed a higher degree of hepatic and adipose tissue inflammation compared to wild-type mice." (PMID 21980496, 2011). "In addition, there was a gradual increase of phosphorylated insulin receptor (p = 0.014) and a gradual decrease of phosphorylated Akt (p<0.001), with increased steatosis severity." (PMID 22359625, 2012). "Farrerol treatment significantly restored the dephosphorylation of INSR by targeting PTPN1 and alleviated the steatosis of HepG2 cells by inhibiting the PI3K/AKT signalling pathway." (PMID 39289804, 2024).
gestational diabetes (8 papers, 2016 to 2025). Carbohydrate intolerance first diagnosed during pregnancy. "Importantly, gestational diabetes has been implicated in abnormal insulin receptor signaling in placenta." (PMID 26090578, 2016). "Non-insulin-dependent diabetes (type 2 diabetes, T2D) is characterized primarily by reduced insulin receptor sensitivity, and gestational diabetes (GD) occurs during pregnancy." (PMID 40427440, 2025). "In humans, it has been reported that increased DNA methylation is involved in decreased insulin receptor expression in the adipose tissue of infants born to mother with gestational diabetes." (PMID 34177815, 2021). "In gestational diabetes, the mRNA levels of INSR were significantly reduced in both SAT and VAT, with a relevant drop of INSR protein content in VAT, displaying an inverse association with key maternal and neonatal anthropometric/metabolic outcomes." (PMID 30754657, 2019). "Both higher birth weight and gestational diabetes may serve as markers for aspects of the fetal environment, such as increased levels of growth factors or insulin receptor activation leading to IGF-I overproduction." (PMID 40204946, 2025).
heart failure (8 papers, 2010 to 2023). Inability of the heart to pump blood at an adequate rate to meet tissue metabolic requirements. "These genes included IRS1 encoding insulin receptor substrate, the major component of insulin signaling, the loss of which leads to heart failure, as well as ADCY8 encoding cAMP producing adenylate cyclase 8, which protects against cardiac stress." (PMID 37110207, 2023). "Studies have shown that excessive activation of cardiac FoxO1 causes DCM and heart failure via insulin receptor substrate downregulation." (PMID 36843604, 2023). "The FRMD4B gene is part of the GRP1 signaling complex, thereby recruited in response to insulin receptor signaling, but genetic variants have also been associated with heart failure." (PMID 25071839, 2014).
insulinoma (8 papers, 2011 to 2025). "New agents under investigation as treatment options for malignant insulinomas associated with refractory hypoglycemia include anti-insulin receptor monoclonal antibodies, oral somatostatin receptor drugs, and soluble stable glucagon." (PMID 36494838, 2022). "In adults, HH can be due to an insulinoma, pancreatogenous hypoglycaemic syndrome, post gastric-bypass surgery for morbid obesity as well as to mutations in insulin receptor gene." (PMID 23032149, 2012). "The presence of insulin or insulin receptor antibodies can distinguish insulin autoimmune hypoglycemia from insulinoma." (PMID 39125476, 2024). "Previous studies have shown that glucose treatment of insulinoma cells results in activation of the insulin receptor substrate-PI3-kinase-Akt pathway that serves to protect against β-cell death." (PMID 21541314, 2011). "Mouse insulinoma cells and primary islets were treated with palmitate at increasing glucose and effects on apoptosis, endoplasmic reticulum (ER) stress and insulin receptor substrate (IRS) signaling were examined." (PMID 21541314, 2011). "Management involved the administration of intravenous dextrose and a thorough workup (72 h fasting test, C-peptide, insulin, proinsulin, and anti-insulin receptor antibodies) to rule out insulinoma." (PMID 40981133, 2025).